BRAF (B-Raf proto-oncogene, serine/threonine kinase)
Diseases named in the same sentence as BRAF in open-access papers (continued):
Sharing a sentence is not in itself a finding about the gene and the disease.
melanoma (continued). "In addition to BRAF, other genes have been found mutated in sporadic melanomas including NRAS, TERT, NF1, and KIT." (PMID 37627054, 2023). "Overall, these data indicate for the first time that the expression of the lysosomal sphingolipid-metabolizing enzyme GALC may exert a pro-oncogenic impact on the proteomic landscape in BRAF-mutated human melanoma." (PMID 37445731, 2023). "BRAF mutations occur in ~50% of melanomas, the majority of which are BRAFV600E." (PMID 36678596, 2023). "With these findings in mind, we reasoned that combining phenformin with a RAF inhibitor would lead to enhanced responses in the treatment of patients with BRAF V600-mutated melanoma and could overcome resistance to the RAF inhibitor." (PMID 37930123, 2023). "The use of two cell lines harboring the same driver mutation appeared to be necessary given the well-known tumor heterogeneity and would have allowed us to define common and individual protein profiles modulated by GALC overexpression in BRAF-mutated human melanoma cells." (PMID 37445731, 2023). "Previous studies have reported that lipid metabolism and bioactive oxylipin metabolism may be implicated in melanoma resistance to BRAF inhibitors, consistent with our findings that the ether lipid metabolism was enriched in BRAF-mutant melanoma." (PMID 37205993, 2023). "Melanoma epidemiology and BRAF-mutation frequency are heterogeneous and affected by ethnicity." (PMID 36998456, 2023). "Melanoma development could be governed by driver mutations such as BRAF, H/N/K-RAS, and C-KIT and can be associated with secondary genetic or epigenetic alterations that may affect tumor suppression pathways." (PMID 37174072, 2023). "Moreover, a mutational analysis of 95 female genital tract melanomas showed that BRAF mutation, which is often found in CM, is more often detected in vulvar MM compared with vaginal MM, respectively, in 28% and 9% of cases." (PMID 36900332, 2023). "Moreover, upregulation of NF-κB has been found in melanomas exhibiting BRAF mutations, and it promotes EMT, suggesting a role for both MAPK and PI3K signaling in NF-κB activation." (PMID 37189846, 2023). "More than 20 BRAF mutations have been described in melanoma." (PMID 36982192, 2023). "Notably, approximately 40% of newly diagnosed melanomas harbor BRAF oncogenic mutation (V600E and V600K as the most frequent)." (PMID 37888038, 2023). "The most common oncogenic mutations in melanoma cells are BRAF and NRAS mutations." (PMID 37627116, 2023). "Between 40 and 60% of melanomas harbor a targetable mutation in the gene BRAF, e.g., BRAF V600E." (PMID 37513847, 2023). "Histopathology revealed malignant melanoma (Breslow: 9.2 mm) with BRAF mutation." (PMID 37670317, 2023). "The pro-fibrotic stroma recently characterized in BRAF-mutant melanoma treated with TT is the hallmark of other solid malignancies, and in addition to promote tumor initiation, metastatic dissemination and drug resistance, it has been described to be responsible for immune evasion." (PMID 36774337, 2023). "Additionally, PTEN loss-of-function is involved in acquired resistance to BRAF inhibitors in BRAF-mutated melanomas." (PMID 37958863, 2023). "For early-stage BRAF-mutated melanoma, assessing whether patients should receive rather adjuvant BRAF inhibition due to low eTILs instead of immunotherapy is important." (PMID 37295047, 2023). "Importantly, BRAF mutations in melanoma affect metabolism via the hypoxia-inducible factor 1 (HIF-1), which is the key oxygen sensor and principal regulator of hypoxia-mediated gene response, along with HIF-2." (PMID 37895015, 2023). "We found that miR-195-5p overexpression in BRAF-mutated melanoma cells causes an increase in the expression levels of some EVs biogenesis-related genes like RAB27b, RAB31, and/or FLOT2, which was accompanied by a consequent increase in CD63 and CD9 positive EVs secretion." (PMID 37174717, 2023).
melanoma (continued). "Finally, we established that TERT inhibition is a therapeutic option in V600E-BRAF-mutated melanoma with acquired resistance to BRAF inhibition." (PMID 37296851, 2023). "BRAF-mutated melanoma may be connected to a significantly shorter life expectancy and poor prognostic indicators; however, this is currently under investigation." (PMID 37629523, 2023). "Crizotinib may be used as a complementary therapy for melanoma with BRAF mutations by inhibiting the mTOR/Insulin signaling pathway." (PMID 37770477, 2023). "PDE4D was demonstrated to be a tumor-promoting factor in prostate cancer and BRAF-mutated melanoma." (PMID 36816023, 2023). "Histopathology showed malignant melanoma (Breslow: 5.5 mm) with BRAF V600 mutation." (PMID 37670317, 2023). "First, approximately 40–60% of all patients with melanoma harbor BRAF variants." (PMID 37976135, 2023). "MiR-193a-3p linked to BRAF mutation status in melanoma tissues." (PMID 37298110, 2023). "A2058 and A375 cells express intermediate levels of GALC mRNA and protein when compared to other human melanoma cell lines, being therefore suitable for assessing the impact of the upregulation of this enzyme on the biological behavior of human melanoma cells in a BRAF-mutated background." (PMID 37445731, 2023). "The herein reported model has been realized by treating with PLX4032, for six months, patient-derived BRAF-mutated melanoma cells in order to obtain a reliable model of acquired PLX4032 resistance that could be predictive of patient’s treatment responses." (PMID 37534247, 2023). "Therefore, the aim of the present study was to test the applicability of this combination in vivo using three xenograft models as well as to bolster the concept that BRAF inhibitors enhanced the antitumor efficacy of MEK inhibitors in NRAS-mutated melanoma." (PMID 38067230, 2023). "Notably, our previous study has shown that when BRAF-mutated melanoma cell lines are treated with low micromolar concentrations of HPF, among many other proteins, they experience a depletion of GPX-4." (PMID 37507910, 2023). "Hence, it was proposed that for multiple primary melanomas or metastatic cases, multiple specimens are preferred over a single primary specimen for the BRAF mutation detection." (PMID 38201554, 2023). "Regarding the involvement of the MAPKs’ signaling pathways in cancer, it is known that approximately 50% of melanomas exhibit mutations in the BRAF oncogene, leading to constitutive activation of the Extracellular Signal-Regulated Kinases 1 and 2 (ERK1/2) pathway and uncontrolled proliferation." (PMID 38004419, 2023). "The phase 3, double-blind, placebo-controlled COMBI-AD trial demonstrated a significantly longer recurrence-free survival (RFS) after 12 months for adjuvant dabrafenib plus trametinib compared to placebo in patients with resected stage III melanoma with BRAF V600E or V600K mutations." (PMID 36672358, 2023). "However, mucosal melanomas tend to differ from their cutaneous counterparts in terms of molecular profiling; albeit showing a heterogeneous molecular profile, they have lower BRAF and TERT, and relatively higher NRAS and KIT mutation frequencies." (PMID 35642348, 2023). "BRAF inhibitor response in melanoma is variable, and BRAF mutated patients often relapse." (PMID 37838724, 2023). "Thus, this study explored a potential universal efficacy of RSK inhibitors in malignant melanoma with MAPK pathway hyperactivation – including RAS- and NF-1-mutated in addition to BRAF-mutated melanomas." (PMID 37464364, 2023). "BRAF/MEK targeted therapies, such as dabrafenib and trametinib, have become the standard of care for the treatment of melanoma brain metastases with a BRAF-MEK pathway driver mutation and currently have histology-agnostic approval for tumors harboring the BRAF V600E mutation." (PMID 37373596, 2023).
melanoma (continued). "The phase II TRICOTEL study showed that intracranial activity could be obtained by adding vemurafenib to cobimetinib in patients with BRAF V600-mutated melanoma." (PMID 36995534, 2023). "Therapeutic options for BRAF-mutated melanoma in the first line include combinations of ICIs, nivolumab alone or with ipilimumab and pembrolizumab, or BRAF and MEK inhibitors (BRAFi/MEKi), dabrafenib and trametinib, encorafenib and binimetinib, and vemurafenib and cobimetinib." (PMID 36995534, 2023). "The sensitivity of melanoma cells to targeted inhibitors and immunotherapies has been shown to be associated with different levels of cancer cell differentiation (differentiated phenotypes exhibit higher sensitivity to BRAF inhibitors)." (PMID 36674631, 2023). "BRAF is a serine/threonine kinase that harbors activating mutations in 60% of melanomas." (PMID 36872348, 2023). "Likewise, miR-579-3p was downregulated in tumour tissues derived from BRAF-mutated melanoma patients with acquired resistance to BRAFi and its expression correlated with a poor prognosis." (PMID 37627054, 2023). "Of the 93 patients with melanoma, 35 (38%) had a BRAF V600E mutation." (PMID 37370865, 2023). "Interestingly, BRAF mutations were found in both the nevus and melanoma parts in melanoma biopsies, while activation of the PI3K pathway was detected in the melanoma portions only." (PMID 37762707, 2023). "Additional pre-clinical work suggests that phenformin mediated AMPK activation can directly inhibit the mitogen-activated protein kinase (MAPK) pathway and provide a synergistic effect in combination with BRAF/MEK inhibitors in melanoma tumors with BRAF V600E/K mutations." (PMID 37397389, 2023). "Notably, depletion of CRAF levels compromises the viability of melanoma cells with either BRAFV600K mutation or wide-type BRAF." (PMID 38111008, 2023). "However, it cannot be applied for BRAF-WT melanoma, and also, in BRAF-mutated melanoma, tumor relapse often follows after an initial phase of tumor regression." (PMID 36902392, 2023). "Similarly, BM is more likely to present asymptomatically at diagnosis in oncogene-addicted NSCLC and BRAF-mutated melanoma, which emphasizes the importance of molecular subtype-based screening." (PMID 37484759, 2023). "These mutations co-occur frequently with BRAF alterations and are correlated with increased aggressiveness and poorer prognosis suggesting a functional link between BRAF signaling and telomerase reactivation in melanoma." (PMID 37296851, 2023). "Fifty-nine patients with BRAF-mutated melanoma received subsequent therapy after failing ICI." (PMID 37887546, 2023). "Furthermore, BRAF V600K positive melanoma is considered to be more aggressive than V600E ones, underlying that the mutational load of BRAF-mutated melanoma should be considered as a key aspect in melanoma management." (PMID 37627054, 2023). "Mutations in BRAF are commonly found in melanoma, thyroid cancer, and colorectal cancer." (PMID 37240450, 2023). "Regarding BRAF, twenty-three melanomas carried mutations at the hotspot position V600." (PMID 36765773, 2023). "BRAF is one of the most frequently mutated oncogenes recognised in melanoma." (PMID 37627054, 2023). "The United States Food and Drug Administration (FDA) approved the combination of PD-L1 inhibitor atezolizumab with BRAF inhibitor vemurafenib plus MEK inhibitor cobimetinib for the first-line treatment of advanced melanoma patients with BRAFV600 mutations in 2020." (PMID 37345194, 2023). "In a study of melanoma samples harboring the BRAF V600E mutation, this approach could distinguish responders and non-responders to dabrafenib monotherapy." (PMID 37760447, 2023). "Half of melanoma cases are characterized by the mutation BRAF V600." (PMID 37241207, 2023). "Notably, the dormancy state is connected with cell plasticity in NRAS- and BRAF-mutated melanomas that lead to increased survival or therapy resistance." (PMID 37504268, 2023).
melanoma (continued). "Melanomas frequently have either mutations in N-Ras or its downstream effector BRAF." (PMID 37114375, 2023). "Moreover, advanced melanoma with acquired BRAF (V600) mutations is resistant to initially effective BRAF/MEK inhibitors, which is the main reason restricting patient benefit." (PMID 37007062, 2023). "To investigate whether oncogenic BRAF targeting associated with VEGFA removal similarly modulate the adaptive immunity in D4M melanomas, we analyzed by flow cytometry the number of tumors infiltrating T cells after 12 days of treatment." (PMID 37183363, 2023). "Therefore, we investigated HPF effects on three melanoma cell lines harboring the dangerous but frequent mutation in the BRAF gene, which makes downstream proliferative signaling pathways constitutively active." (PMID 36674794, 2023). "When extrapolating from the metastatic melanoma literature, these observations, supporting neoadjuvant immunotherapy over targeted therapy, were further corroborated, in the DREAMseq trial, which investigated which initial treatment for BRAF-mutated melanoma was more effective." (PMID 37444454, 2023). "Targeted therapy and PD-1/L1 inhibitors are the main treatments for BRAF V600-mutated melanomas." (PMID 37215493, 2023). "Few months later, a TT drug called Vemurafenib (a BRAF inhibitor, BRAFi) also demonstrated clinical benefits for melanoma patients having an actionable BRAF V600E/K mutation and it rapidly became standard of care for these patients, which represent about half of all metastatic melanomas." (PMID 37025593, 2023). "BRAF mutations are common in melanoma, ovarian cancer, thyroid cancer, and colorectal cancer." (PMID 36759818, 2023). "However, the difference between BRAF-mutated melanomas and thyroid cancers on STAG2 inactivation-induced resistance mechanism still need to be further investigated." (PMID 37479689, 2023). "Therefore, we aimed to study for the first time the anti-tumor activity of the GAPDH inhibitor GP-2250 in BRAF-mutated melanoma cell lines and benign melanocytes." (PMID 37895015, 2023). "Importantly, comparable effects were obtained in BRAF-mutated and BRAF-WT melanoma cells, indicating that this therapeutic gap can be overcome." (PMID 36902392, 2023). "Mutation in BRAF, a serine-threonine kinase involved in the mitogen-activated protein kinase signal transduction pathway, is one of the most common oncogenic mutations in melanoma." (PMID 37205993, 2023). "SK-MEL-28 is a lineage of human melanoma that harbors the BRAF V600E mutation, which enhances and selects sensitivity to mitogen-activated protein kinase kinase (MEK) inhibition compared to “wild-type” cells, causing deregulation of the proliferation, survival, and metastasis of cancer cells." (PMID 37445794, 2023). "In some cases, MITF mutations have been observed in melanomas that also harbor BRAF mutations." (PMID 37504268, 2023). "BRAF-mutated melanoma cells were recently shown to display high CDK12 activity." (PMID 38104154, 2023). "In addition, melanoma patients were also divided into four subtypes based on some mutated genes, and they were B-Raf Proto-Oncogene, Serine/Threonine Kinase (BRAF) hotspot, RAS hotspot, Neurofibromin 1 (NF1) mutant, and Triple-WT (wild-type)." (PMID 37036471, 2023). "BRAF mutations are seen in up to 10% of various cancers, including melanoma (40–60%), thyroid cancer (50%), glioma (11%), colorectal carcinoma (10%), cholangiocarcinoma (6%), non-small cell lung carcinoma (NSCLC) (3%), hairy cell leukemia, multiple myeloma, and Langerhans cell histiocytosis." (PMID 36801912, 2023). "Similarly, genetic testing has greatly benefited melanoma diagnosis and treatment, primarily due to the high prevalence of BRAF hot spot mutations and other well-characterized genetic alterations." (PMID 37841001, 2023).
melanoma (continued). "Ninety‐three patients with resected stage III melanoma with BRAF V600E mutation were identified in our study, including 25 patients receiving adjuvant anti‐PD‐1 immunotherapy (PD‐1), 25 receiving adjuvant D + T, 23 receiving V, and 20 patients with observation‐only (OBS)." (PMID 37016119, 2023). "Moreover, this review focuses on the mechanisms responsible for resistance to targeted therapies in BRAF-mutated melanoma and provides an overview of circulating biomarkers including circulating tumour cells, circulating tumour DNA, and non-coding RNAs." (PMID 37627054, 2023). "Approximately 50% of melanoma patients have an activating mutation in the BRAF gene." (PMID 37504313, 2023). "However, approximately 3–5% of melanomas harbor rare mutations in the BRAF gene outside the V600 codon (non-V600 mutations)." (PMID 37569660, 2023). "However, using a large panel of NRAS- and BRAF-mutated cell lines as a model for MAPK-dependent melanoma, we show that MALAT1 expression is essential for melanoma colony formation, cell growth, and tumor growth." (PMID 37235843, 2023). "The expression pattern of EMT-transcription factors, such as Slug and ZEB1, revealed an opposite trend, which is typical of melanoma cells; they could mediate a phenotype switch associated with resistance to the BRAF inhibitor." (PMID 37189846, 2023). "We therefore envision multiple mechanisms by which biguanides might enhance the effect of RAF inhibitors on BRAF V600-mutated melanoma." (PMID 37930123, 2023). "The results of the present work extend previous observations about a pro-oncogenic role of GALC in Braf wildtype murine melanoma cells by demonstrating that GALC overexpression increases the tumorigenic potential of human melanoma cells harboring the tumor-driving BRAF(V600E) mutation." (PMID 37445731, 2023). "Nivolumab was granted FDA approval on December 22, 2014, for the treatment of individuals with metastatic or unresectable melanoma whose illness progressed even after ipilimumab therapy, and in patients who tested positive for a BRAF V600 mutation following treatment with a BRAF inhibitor." (PMID 37849799, 2023). "Some insight in such difficult-to-treat melanoma patients was gained through the COMBI-mb trial, recruiting within four cohorts 125 patients in total with either asymptomatic (pre-/untreated), rare mutation types (other than BRAF V600) or symptomatic brain mutations arising from melanoma." (PMID 37760406, 2023). "To test this hypothesis, we established an experimental in vitro model of human BRAF-mutated melanoma cell lines with acquired resistance to BRAF and MEK inhibitors." (PMID 37296851, 2023). "Lower survival was associated with the line of the ICB treatment (log-rank p< 0.001), the type of ICB used (log-rank p = 0.013), the histological melanoma subtype (log-rank p = 0.009), BRAF V600 mutation status (log-rank p = 0.009) and PD-L1 expression (log-rank p = 0.049)." (PMID 36980349, 2023). "The introduction of targeted inhibitors for the mutated oncogenic proteins that drive melanoma onset and aggressiveness, such as BRAF (vemurafenib and dabrafenib), MEK (trametinib and cobimetinib), and c-KIT (imatinib), has improved the durability of treatment response." (PMID 37176114, 2023). "In the case of the TCGA Pan-Cancer Atlas (448 melanoma samples in total), among the 35 BRAF V600K mutated samples, 5 also had the R264C mutation in PPP6C (14.3%), while only 2/158 (1.3%) samples carried concomitant BRAF V600E and PPP6C R264C mutations (Fisher’s Exact Test—p-value = 0.00242)." (PMID 36765773, 2023). "However, acquired resistance to treatment with BRAF V600E kinase inhibitors, such as vemurafenib, and the side effects of some other drugs used in BRAF-mutated melanoma cause several clinical problems." (PMID 37446932, 2023). "In BRAF-mutated melanoma, the choice of first-line treatment is based on clinical parameters." (PMID 38201531, 2023).